CD44 (CD44 molecule (IN blood group))
Diseases named in the same sentence as CD44 in open-access papers (continued):
Sharing a sentence is not in itself a finding about the gene and the disease.
tumor (continued). "As a result, it is imperative to ascertain the importance of each CD44 variant and its correlation to tumor progression." (PMID 38672650, 2024). "We showed that tumors with tumor‐associated wild‐type P. aeruginosa had increased CD44 biomarker expression compared to tumor cells with tumor‐associated ΔpvdA mutant." (PMID 39135304, 2024). "In vivo limiting dilution assays revealed that the loss of PCAT6 dramatically reduced tumor incidence, and reduced CD44+ breast CSCs, c‐MYC, and Ki67 were detected in PCAT6 knockdown cell‐formed xenografts compared with control xenografts." (PMID 38626369, 2024). "Particularly, numerous lines of evidence suggest that elevated CD44 expression is associated with the CSC-like phenotypes across various tumor types." (PMID 39030572, 2024). "CD44 was identified as the initial marker of CSCs across various cancer types, and a high prevalence of CD44-positive cells is closely associated with tumour recurrence and increased malignancy." (PMID 38920995, 2024). "The functional involvement of CD44 and its variants in tumor progression made them both CSC markers and therapeutic targets." (PMID 38609981, 2024). "CHI3L1 is released into the TME, interacts with CD44 expressed on tumour‐associated macrophages, and activates the AKT pathway, thus promoting polarization of M2 macrophages." (PMID 38809929, 2024). "The most spliced gene was SNHG17 with >25 splice forms and tumour associated splice events of CD44, STAT1, FAS, and IRF1 further confirming the JAK-STAT pathway enrichment from GSEA." (PMID 37091785, 2023). "Specific CD44 variant isoforms are selectively expressed in normal colonic SCs and become overexpressed in CRCs during tumor development." (PMID 37005380, 2023). "In vivo studies on human ovarian xenografts confirmed that suppression of CD44 was responsible for increased tumor susceptibility to platinum-derived treatments leading to nearly complete tumor reduction." (PMID 37287910, 2023). "In MEC, intense CD44 and Bmi-1 expression was observed in the tumor invasive front, while Oct4 and Nanog was highly associated with perineural invasion in vivo." (PMID 36726797, 2023). "Then, the potential correlation of CD44 with tumor mutational burden (TMB) and microsatellite instability (MSI) was evaluated." (PMID 37117249, 2023). "Several lines of evidence suggest that a small fraction of tCSC marked by elevated CD44 expression exist within this class of neoplasm linked with baseline tumor growth, metastasis, and resistance mechanisms." (PMID 37655661, 2023). "Previously, it was mentioned that an increase in hepatic stem cell protein expression of cytokeratin 19, CD133, and CD44 is closely associated with tumor angiogenesis and poor prognosis." (PMID 37835585, 2023). "The loss of CD44 expression was associated with greater tumor aggressiveness and positive CD44 expression was associated with a lower Gleason’s grade and vice versa." (PMID 37461792, 2023). "The tumour-promoting roles of HA are linked to its interaction with two main receptors, CD44 and HMMR (RHAMM)." (PMID 37673961, 2023). "The CD44 antigen has been traditionally used in liquid biopsy as lead marker to identify tumor-derived epithelial circulating tumor stem cells based on its association with multi-lineage differentiation and the potential of self-renewal." (PMID 36100762, 2023). "(ii) HMW-HA blocks cell migration by enhancing the co-association between NF2 (also known as Merlin protein) and CD44, which activates the tumor suppressor properties of CD44 (CD44-dependent mechanism)." (PMID 37511533, 2023). "Stem-like tumor cells are generally associated with increased expression of stem cell surface markers such as CD44 and CD133." (PMID 37108495, 2023).
tumor (continued). "CD44, a receptor of hyaluronic acid, has higher expression in many tumor cells than in normal tissues and is associated with the tumorigenicity, invasiveness, and lymphatic metastasis of tumor cells." (PMID 37202657, 2023). "Osteopontin is reported to be an integral part of this hyaluronan–CD44–Ezrin complex, where the malignant secretion of osteopontin and CD44 variant isoforms has caused the migration of tumor cells to specific sites of metastasis formation." (PMID 37371090, 2023). "Another study revealed that heightened CD44 expression was associated with more aggressive tumor behavior, progression, and unfavorable overall survival outcomes in ccRCC patients, but not in those with papillary and chromophobe RCC." (PMID 37509716, 2023). "About the tumor stage, CD44 expression in organoids was significantly associated with T3 tumors compared to Ta and to T2 (p-value <0.0001)." (PMID 37072390, 2023). "An attempt was made to assess the diagnostic utility of CD44/CD24 combination in tumor development, metastasis, and overall survival of patients with OSCC." (PMID 37664387, 2023). "The snRNAseq demonstrated a significant loss of cellular clusters in the Sel‐GemPac‐treated mice tumours including the CD44+ stem cell population." (PMID 38131168, 2023). "CD44 showed an increase in exon usage to result in tumour associated forms and IRF1 with loss of DNA binding region." (PMID 37091785, 2023). "In the past CD44 was identified as a risk gene for different tumor entities and a switch in CD44 isoform expression towards isoform CD44s associates with epithelial to mesenchymal transition (EMT) and cancer cell invasion." (PMID 36876041, 2023). "Populi and Salicis extracts at a dilution of 1:160,000, which had been shown to cause the strongest inhibitory effects on tumor growth and proliferation on the tumor cells, were chosen to evaluate their effects on integrins and CD44 in all three cell lines." (PMID 37835543, 2023). "The presence of CD44-positive tumours was associated with significantly reduced disease-free (p ≤ 0.001) and overall survival (p ≤ 0.001)." (PMID 38201468, 2023). "Further, CD44 has been linked to the sphere-forming, self-renewing and tumor-initiating potential of OC cells." (PMID 37634008, 2023). "As demonstrated, most of the CD44+CD24− BCSCs were located at the invasive edge of the tumor mass, indicating that their presence is associated with enhanced aggressive invasiveness." (PMID 36768876, 2023). "Variable expression levels of CD44 between tumor and adjacent normal tissues were identified in pan-cancer datasets, further survival analysis revealed that CD44 expression was associated with multiple clinical annotations and survival indicators." (PMID 37117249, 2023). "CD44 is overexpressed in cancer stem cells, and a study suggested that alternatively spliced variants participate in tumor progression." (PMID 36797708, 2023). "We further investigated the association between VEGFA/CTNNB1/MMP7/CD44 oncogenic expressions with selected immune cells in the tumor microenvironment (TME)." (PMID 36672201, 2023). "In our study, the inhibition of VEGF with siRNA or bevacizumab in GSCs also markedly increased the expressions of both CD44 and cMET and caused much higher tumor invasion than the control." (PMID 37835592, 2023). "We measured the levels of infiltration of CD163 + M2-TAMs in 92 ESCC tissues and found that increased infiltration of M2-TAMs in the tumor stroma was associated with a poor prognosis in patients as well as the expression levels of CD44 and OCT4." (PMID 36641471, 2023). "CD44 has multiple isoforms including CD44 standard (CD44s) and CD44 variants (CD44v), which have common and unique functions in tumor development." (PMID 37176118, 2023). "As a stem cell marker, c-Met shows a higher accuracy in association with CD44 since the co-expression of both markers identified malignant cells with a higher tumour-initiating capacity." (PMID 37108193, 2023).
tumor (continued). "Nonetheless, some researchers advocated the expression of CD44 as a biomarker associated with some clinicopathological features of the tumor, such as high-grade, more advanced FIGO stage, or the presence of residual disease and drug resistance." (PMID 36768723, 2023). "Meanwhile, GC tissues also highly expressed glycolysis-associated protein GLUT1 and tumor cell stemness marker CD44." (PMID 37980488, 2023). "CD44 (cluster of differentiation-44) is an adhesion molecule associated with tumor occurrence and metastasis, effectively targeted by chitosan oligosaccharide (CO)." (PMID 38139233, 2023). "There are a number of receptors that are overexpressed by cancer cells, one being the cell surface glycoprotein CD44 that is associated with tumor progression, metastasis, and resistance to therapy." (PMID 37626666, 2023). "Full-length CD44 exerts a tumor-suppressive function and is overexpressed in benign prostate epithelium, while CD44 splice variants (CD44v7-10) exhibit pro-invasive activity and are overexpressed in PCa." (PMID 37370750, 2023). "In GBM, CD44 has been linked to increasing tumor invasiveness, proliferation, and chemotherapy resistance." (PMID 37174618, 2023). "For elevated serum levels of the soluble extracellular domain of CD44v6 and the CD44 ICD an association with tumor burden, metastasis and poor prognosis in several cancers including gastric, colorectal or breast cancer have been shown." (PMID 36876041, 2023). "Literature has shown that CD44 is related to the tumor metastasis caused by changes in actin cytoskeleton." (PMID 36192574, 2023). "On the other hand, recently soluble CD44 shed from the cancer cell surface promotes tumor metastasis by triggering macrophage IL-1 production in tumor associated macrophage (TAM)." (PMID 37098074, 2023). "The antibody-mediated blockade of CD44 signaling potentiated the suppressive effects of NK cells on tumor growth associated with increased heterotypic CIC formation, suggesting a new potential approach for cancer immunotherapy." (PMID 37511762, 2023). "The CD44 isoforms include the standard version (CD44s) and larger variants, collectively referred to as CD44v, which are particularly frequent in tumor cells." (PMID 37958334, 2023). "We identified the pivotal role of tumor-associated fibroblasts in the brain metastatic tissues as well as the collagen/fibronectin-CD44/integrin αVβ8/syndecans ligand-receptor axis which serve as the molecular underpins in the TME." (PMID 37479733, 2023). "It was found that the effect of TAM (tumor-associated macrophages) on CSCs function was dependent on HA-CD44 interaction and on CD44 isoform expression." (PMID 37316699, 2023). "At the same time, clusters of tumor cells showed the stable expression of stemness genes (CD44, PROM1) and genes encoding proteins involved in matrix degradation (MMPs)." (PMID 36674951, 2023). "The SPP1/CD44 interaction has been shown to be associated with promoting cell proliferation and stemness of tumor cells." (PMID 37583898, 2023). "The available data suggest that CD44 plays a relevant role in the regulation of cell migration/cell invasion processes associated with tumor malignancy." (PMID 37511533, 2023). "Expression of CD44, a positive regulator of PD-L1 in lung cancer, in the tumour compartment was associated with longer PFS in multivariate analysis." (PMID 37835491, 2023). "As higher CD44 expression in the tumor periphery correlates with higher risk of GBM invasion, the present study analyzed the relationship between CD44 expression and magnetic resonance imaging (MRI)-based invasiveness of GBM on a large scale." (PMID 37760811, 2023). "An inverse relationship between tumor staging and CD44 expression was observed with positive CD44 expression in lower tumor staging which implies loss of CD44 expression was associated with greater tumor aggressiveness." (PMID 37461792, 2023).
tumor (continued). "IHC staining results further confirmed that the expression of CD44 in tumor cells was positively associated with the number of CD68+ macrophages and CD163+ macrophages (P < 0.05)." (PMID 37316699, 2023). "In the present review, we aimed to assess the diagnostic utility of the CD44/CD24 combination in tumor development and metastasis in OSCC." (PMID 37664387, 2023). "CD44 is one of the main prostate CSC tumor markers, and its high expression has been associated with tumor proliferation, stemness gene expression, and metastatic colonization." (PMID 37663388, 2023). "On the other hand, downregulation or inhibition of HA and CD44 expression has been found to promote M1 polarization, which is associated with pro-inflammatory and anti-tumor activities." (PMID 38332915, 2023). "Western blotting analysis confirmed the presence of the tumor-promoting marker CD44, programmed death ligand 1 (PD-L1), and the tumor-associated antigen EphA247." (PMID 38140108, 2023). "CD44 expression suggests that the tumor is in a well-differentiated and gland-forming state as compared to Gleason's grade and its loss suggests tumor aggressiveness." (PMID 37461792, 2023). "Targeting of Merlin to the plasma membrane seems to be crucial for its major tumor-suppressive functions; this is facilitated by interactions with membrane-associated proteins, including CD44 (cluster of differentiation 44)." (PMID 37174657, 2023). "Based on the importance of TAM in cancer progression, in our IHC validation analysis, high CD44 expression of tumor cells was associated with high levels of CD68 + macrophages." (PMID 37316699, 2023). "Although CD44 is expressed in normal cells, its alternative splicing isoforms, including CD44 variant 6 (CD44v6), are upregulated in tumor cells, contributing to tumor cell migration and metastasis by interacting with c-Met111." (PMID 37258584, 2023). "More importantly, some biomarkers have been linked to a specific tumour, for example, CD44, which is found mainly in colorectal and haematological cancer." (PMID 36415383, 2022). "CD44 is also associated with downregulation of Lats1/2 apoptotic pathway that results in increased tumor metastasis and resistance to drug therapy." (PMID 36185622, 2022). "Further, CHI3L1 were released into the tumor microenvironment (TME) and interacted with CD44 expressed on tumor-associated macrophages to activate AKT pathway, thereby contributing to M2 macrophage polarization." (PMID 36276655, 2022). "Once the HA was exposed, uptake by CD-44-expressing tumor cells and tumor-associated macrophages (TAMs) occurred." (PMID 36365245, 2022). "Recent studies have shown that abnormal levels and variant forms of CD44 are expressed in a variety of tumor types." (PMID 36389678, 2022). "Tumor-spheroid formation in vitro is also associated with overexpression of CD44, CD133, Sox2, Nanog, and Oct-3/4." (PMID 36274852, 2022). "Studies have indicated that different CD44 variant isoforms play a crucial role in tumor progression." (PMID 35267625, 2022). "It has been reported that SPP1 can bind to various integrins or certain variants of CD44 and activate downstream signaling pathways to promote tumor progression." (PMID 36612160, 2022). "CD44 activity is vital as a variant of this receptor (CD44v) is overexpressed on the surface of many cancer cells, such as epithelial tumour cells, and specifically binds HA." (PMID 36080515, 2022). "Several studies have demonstrated that HNSCC tumours enriched with CD44-positive cells are associated with local recurrence after chemo- and radio-therapy." (PMID 35055060, 2022). "FACS analysis also demonstrated that tumor associated CD8+ T cell had CD44+ memory T cell phenotype." (PMID 35013322, 2022). "A variant of CD44, a hyaluronic acid receptor (CD44v8-10), was identified as the predominant CD44 variant expressed in GC cells and contributes to tumor progression, possibly by enhancing oxidative stress defense." (PMID 36010940, 2022).
tumor (continued). "Deciphering further EMT-associated mechanisms controlling TF expression in tumor cells, we examined here a potential impact of CD44 in TF regulation." (PMID 35805061, 2022). "Univariate analysis showed that Ki-67, mitotic index, OTP, CD44, and tumor diameter were associated with development of distant metastases." (PMID 35805004, 2022). "Here, the current study shows that the CD44-Stat3 signaling pathway is robustly associated with tumor progression and radiation resistance." (PMID 36678534, 2022). "Remarkably, antibody-mediated blockade of CD44 signaling potentiated the suppressive effects of NK cells on tumor growth associated with increased heterotypic CIC formation." (PMID 35436988, 2022). "Increased levels of tumor-associated HA promote tumor invasion and metastasis by signaling through its receptors CD44 and RHAMM." (PMID 36581895, 2022). "CD44 has been implicated in malignant processes including cell motility, tumor growth, and angiogenesis." (PMID 36559056, 2022). "Univariate analysis revealed that CD44 (p < 0.001), Ki-67 (p < 0.001), and tumor diameter (p = 0.026) were significantly associated with disseminated disease at baseline." (PMID 35805004, 2022). "Due to its tumorigenic functions and level of expression often associated with tumor-initiating cells/cancer stem cells, CD44 is considered an early indicator for cancer cell proliferation." (PMID 35762636, 2022). "Disintegration of lipid rafts play positive roles in fighting tumor growth, for example, by inducing Fas oligomerization and apoptosis, or by causing disorder in CD44 localization and thus inhibiting its function in tumor cell migration." (PMID 35163891, 2022). "Upon ectopic CD24 expression, the gene CD44 (encoding cell surface adhesion receptor CD44) was downregulated, which has been shown to be expressed in cancer cells and regulates tumor cell invasion and metastasis." (PMID 36016357, 2022). "Undifferentiated CD44+CD24−/low cells in tumours after chemotherapy were associated with poor outcomes in patients with invasive breast cancer." (PMID 35563449, 2022). "Tumor size (χ2 = 13.41, p < 0.0002) and stage (χ2 = 32.94, p < 0.001) showed highly significant association with CD44 expression." (PMID 35274800, 2022). "In PAAD, an increased expression of CD44, a marker for cancer stem cells, was closely linked to tumor recurrence and a poor prognosis." (PMID 36359832, 2022). "Increased levels of CD44 are associated with invasive properties of tumor cells and predict a poor prognosis in diverse cancer subtypes." (PMID 35955749, 2022). "Tumor-associated HA promotes epithelial-mesenchymal transition by signaling through its receptors (CD44, RHAMM)." (PMID 36581895, 2022). "We measured the mRNA expression of the gene encoding the stem cell marker CD44 in the tumor core and periphery, and calculated the ratio of amounts of CD44 expression in the tumor periphery to those in the tumor core (P/C ratio)." (PMID 35624954, 2022). "To date, CD44s has been the most frequently reported isoform in malignancy, but other CD44 variants (e.g., CD44v) were also found to regulate redox homeostasis and promote neoplasia in several cancer types." (PMID 36499654, 2022). "The results showed that stromal tumor-infiltrating lymphocytes (TILs) percent and the expression levels of CD44, B2M, PTPN11, and TRIM74 were associated with DFS in NPC patients." (PMID 36107539, 2022). "Tumor samples from patients analyzed in this study also supported the association among vasculogenic structures and ‘blood lakes’ formation and CD44 expression." (PMID 35785191, 2022). "Tumor size (p < 0.001), stage (p < 0.001), and treatment response (p < 0.001) showed statistically significant association with CD44 expression." (PMID 35274800, 2022). "Hyaluronic acid-mediated signalling of CD44 associated with tumor metastasis have been widely studied." (PMID 36358852, 2022).